INS (insulin)
Diseases named in the same sentence as INS in open-access papers (continued):
Sharing a sentence is not in itself a finding about the gene and the disease.
type 2 diabetes (continued). "High-fat diet (HFD) is associated with Alzheimer’s disease (AD) and type 2 diabetes risk, which share features such as insulin resistance and amylin deposition." (PMID 37558676, 2023). "Many patients diagnosed with type 1 diabetes who maintain C-peptide in this range can improve blood glucose levels with adjuvant (type 2 diabetes-associated) agents and/or discontinue insulin." (PMID 37728732, 2023). "Nonetheless, prior literature has shown that NAFLD is directly linked to abnormal glucose tolerance, circulating insulin levels, insulin resistance (IR), type 2 diabetes (T2D), and obesity." (PMID 37948568, 2023). "Several epidemiological studies have reported that higher blood TPA levels are associated with higher insulin sensitivity and a lower incidence of type 2 diabetes." (PMID 37571372, 2023). "Type 2 diabetes is a chronic disease caused by an inherited and/or acquired deficiency of insulin by the pancreas or ineffectiveness of the insulin produced." (PMID 36773074, 2023). "Alanine is one of the most abundant amino acids in the circulation and higher levels have been robustly associated with impaired insulin secretion and incident type 2 diabetes." (PMID 38035361, 2023). "The physiological release of insulin is vital for maintaining glucose homeostasis, and disruptions in this process during the initial phase have been linked to the development of type-2 diabetes (T2D)." (PMID 37446104, 2023). "Weight loss improves multiorgan insulin sensitivity and reduces the risk of developing type 2 diabetes." (PMID 37159276, 2023). "Impaired microvascular responses to insulin and acetylcholine in skin confers a higher risk of HFpEF in women with type 2 diabetes." (PMID 37658327, 2023). "Apart from overstimulating insulin secretion, another causative factor largely contributing to the progressive failure of β-cells in type 2 diabetes is sustained hyperglycemia." (PMID 38203600, 2023). "Loss of coordinated insulin production and secretion from pancreatic beta cells is a key pathological feature of both type 1 and type 2 diabetes." (PMID 37537395, 2023). "Overall, the integrative analysis unravels the principal transcriptional alterations underlying the islet deterioration of morphology and insulin secretion along type 2 diabetes progression." (PMID 37816033, 2023). "In particular, in the progression towards type 2 diabetes, impaired beta cell function is linked to higher insulin demand driven by insulin resistance." (PMID 36280617, 2023). "Previous studies have reported α2A-adrenoceptor single nucleotide polymorphism which contributes to increased receptor expression affecting insulin secretion and increasing type 2 diabetes risk." (PMID 38139390, 2023). "Malfunctions in the autoimmune system cause damage to insulin-producing beta cells and insulin resistance due to failing insulin receptors, which are characterized as type 1 and type 2 diabetes, respectively." (PMID 37959677, 2023). "Type 2 diabetes (T2D) accounts for more than 90% of DM cases and is primarily caused by an inappropriate cellular response to insulin." (PMID 38132105, 2023). "Type 2 diabetes develops because of the progressive loss of insulin-secreting cells or tissue resistance to the hormone, where tissues do not absorb insulin and its action in the body does not occur." (PMID 37999402, 2023). "NAFLD is also a risk factor for type 2 diabetes, in part because hepatic cytokines activate insulin signaling in other tissues." (PMID 37134024, 2023). "These types of diets can improve insulin sensitivity, reduce inflammation, and lower the risk of obesity and type 2 diabetes." (PMID 37445852, 2023). "These specific methylation profiles can influence insulin secretion, contribute to weight gain, and increase susceptibility to type 2 diabetes." (PMID 38292775, 2023).
type 2 diabetes (continued). "Type 2 diabetes (T2D) is defined as a chronic metabolic disease featured with insulin resistance and deficiency in insulin secretion, which is associated with additional metabolic disorders such as dyslipidemia and atherosclerosis." (PMID 37322504, 2023). "Defects in insulin processing and granule maturation are linked to pancreatic beta-cell failure during type 2 diabetes (T2D)." (PMID 37460527, 2023). "In people enduring the agony of type 2 diabetes, there is compromised glucose homeostasis, which is caused by reduced insulin secretion or insulin resistance at different levels such as in the muscles, liver, adipocytes, or by anomalies in glucose uptake." (PMID 38094528, 2023). "Of note, this approach in our cohort did produce robust findings for both insulin and inflammation metabolites with risk of type 2 diabetes, a disease that is strongly associated with these biological processes." (PMID 37367904, 2023). "Notwithstanding, in people with type 2 diabetes a higher risk of COVID‐19‐related mortality was observed with a prescription of insulin and a lower risk with MF and SGLT‐2i,5 in line with our findings." (PMID 36099041, 2023). "Obesity always leads to decreased insulin sensitivity, and reduced glucose tolerance in turn, which is the main cause of type 2 diabetes." (PMID 36677779, 2023). "Melatonin inhibits insulin secretion by β-cells, which suggested a link between abnormal melatonin signaling and the risk of type 2 diabetes." (PMID 37138267, 2023). "Impaired insulin-stimulated translocation of GLUT4 to the cell surface is the major defect in muscle and adipose tissue insulin resistance, leading to dysregulated glucose homeostasis and predisposing individuals to type 2 diabetes." (PMID 37248992, 2023). "We tested associations between polygenic risk scores for type 2 diabetes, fasting glucose, fasting insulin and haemoglobin A1c as exposure variables and dementia as outcome variables in 29 139 adults (mean age 55) followed for 20–23 years." (PMID 37091584, 2023). "The results of a systematic review study show that inactivity leads to type 2 diabetes through decreased insulin sensitivity, gradual loss of beta cells, impaired glucose tolerance, and ultimately obesity." (PMID 36998281, 2023). "In one multi-ethnic prospective cohort study of 500 adult patients with type 2 diabetes, the female gender was associated with a two-fold increase in the subsequent use of insulin therapy during the three years of follow-up." (PMID 37858088, 2023). "SGLT2 inhibitors such as dapagliflozin and empagliflozin have been shown to have a significant impact on adipocyte metabolism, energy expenditure, and insulin sensitivity, resulting in weight loss and improved glycemic control in patients with type 2 diabetes." (PMID 37047011, 2023). "Here, we performed a two-sample MR study to comprehensively examine the association of type 2 diabetes and glycemic traits (fasting insulin, fasting glucose, and HbA1c) with testosterone levels." (PMID 37900148, 2023). "Glycemic regulation occurs through several mechanisms, including the participation of the GLUT4 transporter and insulin secretion, whose deficiency can generate insulin resistance evolving to type 2 diabetes." (PMID 37894869, 2023). "Our study demonstrates that in the natural history of type 2 diabetes, progressive beta cell dysfunction is characterised by a progressive increase in ER stress accompanied by an altered insulin processing, finally leading to a loss of beta cell phenotype." (PMID 36280617, 2023). "Type 2 diabetes mellitus (T2DM) is a metabolic disease caused by various etiologies leading to dysfunction of insulin secretion or action." (PMID 36600212, 2023). "Indole-3-propionic acid is associated with enhanced insulin secretion and insulin sensitivity and thereby results in a reduced risk of type 2 diabetes." (PMID 37760793, 2023).
type 2 diabetes (continued). "High fat diet induced obesity leads to impaired insulin access to skeletal muscle and glucose uptake, while polyunsaturated fat-rich diets improve insulin sensitivity and lower the risk of Type 2 diabetes." (PMID 36942499, 2023). "APOC3 promotor variants increase type 2 diabetes risk and the need for insulin treatment, particularly among lean patients." (PMID 37834292, 2023). "On the other hand, the use of metformin (an insulin sensitizer), reduces it, whereas use of sulfonylureas (insulin secretagogues) appears to increase the risk for cancer in individuals with type 2 diabetes." (PMID 36830690, 2023). "Poor sleep quality and duration have been linked to an increased risk of obesity and type 2 diabetes, potentially due to their effects on appetite regulation and insulin sensitivity." (PMID 37445852, 2023). "The subsequently induced synthesis of fetal hemoglobin affects BMI or BMI-associated phenotypes such as type 2 diabetes and insulin secretion." (PMID 37672078, 2023). "Collectively, our data showed that metabolic stress occurring during type 2 diabetes progression induces significant changes in ER stress, leading to impaired insulin synthesis in situ, loss of beta cell identity and beta cell dysfunction." (PMID 36280617, 2023). "For instance, a variant associated with the 85th percentile of z-insulin was located on the SLC28A1 (or CNT1) gene that has been linked to type 2 diabetes." (PMID 37420130, 2023). "Decreased glycine receptor (GlyR) expression in cells from people with type 2 diabetes mellitus (T2DM) is associated with a disruption of glycine-induced insulin secretion." (PMID 37510995, 2023). "Elevated expression of BCL11A in human beta cells was reported to be negatively correlated to insulin secretion, contributing to an increased risk of type 2 diabetes development, making this gene a prominent target for further studies." (PMID 37672078, 2023). "Of all the mechanisms involved in beta cell dysfunction, ER stress represents a determinant link between altered insulin processing and loss of beta cell identity and dysfunction in type 2 diabetes." (PMID 36280617, 2023). "Type 1 diabetes results from the autoimmune destruction of the β-cells of the pancreatic islets and type 2 diabetes is caused from impaired insulin secretion and resistance to the action of insulin." (PMID 37176684, 2023). "Using insulin analogues has been shown in RCTs to reduce the risk of hypoglycaemia, including in people with type 2 diabetes." (PMID 37817166, 2023). "This concept has been positioned at the forefront of diabetes research for several decades to explain the mechanisms underlying muscle insulin resistance and the metabolic energy switch that occurs in obesity and type 2 diabetes." (PMID 37865313, 2023). "Many studies have warned that administering hemin (purified heme salt) can increase cellular toxicity, aggravate the glucose and insulin tolerance, raise the risk of type II diabetes, and even increase the likelihood of developing cancer [53, -55]." (PMID 37734921, 2023). "Type 2 diabetes (T2D), a disease in which affected individuals have elevated blood glucose levels due to insulin impairments, is one of the leading causes of death globally." (PMID 37033268, 2023). "In type 2 diabetes, longer duration of diabetes and increased time since initiation of insulin therapy are both associated with diminishing hypoglycaemia awareness and blunted counterregulation." (PMID 37308751, 2023). "C-peptide is a biologically active short polypeptide (31 amino acids) that serves as a diagnostic biomarker to distinguish between type 1 and type 2 diabetes and is a strong indicator of insulin biosynthesis and insulin resistance syndrome (IRS)." (PMID 37006572, 2023). "Glucose levels, glucose intolerance, insulin levels, triglyceride (TG), and TC levels were examined on week 12, which recapitulated the hallmark features of type 2 diabetes." (PMID 36946337, 2023).
type 2 diabetes (continued). "The deletion of HIPK in the mouse model impaired glucose tolerance and insulin secretion, leading to a higher risk of type 2 diabetes." (PMID 37683138, 2023). "Improved insulin sensitivity is associated with better metabolic health and a reduced risk of type 2 diabetes." (PMID 38274536, 2023). "Women who require pharmacologic treatment, in particular insulin, to control hyperglycemia in pregnancy, are at high risk of type 2 diabetes progression." (PMID 36635082, 2023). "This is significant and indicates the potential of resveratrol to treat various diseases such as type II diabetes linked to impaired insulin action." (PMID 37241737, 2023). "It is worth mentioning that type 2 diabetes has been increasingly recognized as a risk factor for AD through different mechanisms including inflammation, insulin resistance, and hyperglycemia." (PMID 37038622, 2023). "Herein, the FA2B structure negatively associates with insulin levels, but the same structure has been previously found to be increased in type 2 diabetes." (PMID 37079606, 2023). "Type II diabetes (T2D) is a chronic disease condition with high blood glucose level caused by the inability of the pancreas to produce enough insulin to regulate glucose level." (PMID 36672953, 2023). "EXOC6, encoding the exocyst complex component 6, is involved in translocation of the GLUT4 glucose transporter in adipocytes and insulin secretion in pancreatic β-cells, increasing the risk of type 2 diabetes." (PMID 37372445, 2023). "In some patients with type 2 diabetes, the condition becomes more critical, and the pancreas will be exhausted completely, which will further produce lower amounts of insulin, causing higher blood sugar levels." (PMID 37240813, 2023). "GDM has the same risk factors and genetic susceptibility as type 2 diabetes, which is related to IR and impaired insulin secretion." (PMID 35257355, 2023). "Reduced insulin responsiveness is referred to as insulin resistance (IR), which is a typical hallmark of type 2 diabetes, hypertension, lipid metabolic problems, and even cardiovascular disease." (PMID 37575577, 2023). "A major contributor to the clinical inertia in the escalation of insulin therapy among healthcare professionals, and a feared side effect of insulin among people with type 2 diabetes, is the risk of hypoglycemia." (PMID 36631592, 2023). "CAPN10, which encodes calpain 10 and is involved in insulin function and secretion, has been identified as a risk gene for type 2 diabetes, and specific CAPN10 variants have been associated with PCOS." (PMID 37371662, 2023). "The ‘aim’ of this study was to investigate associations between genetic risk markers of type 2 diabetes, fasting glucose, fasting insulin and HbA1c as exposure variables and dementia diagnoses as outcome variables." (PMID 37091584, 2023). "It is well known that having more body fat reduces the effectiveness of insulin and increases the risk of developing type II diabetes in humans." (PMID 37241737, 2023). "Low birth weight arising from of intra uterine stress has been linked with changes in skeletal muscle and pancreatic morphology function, leading to increased skeletal muscle insulin resistance and future risk of type 2 diabetes." (PMID 37215099, 2023). "We also identified the CAPN9 gene, which contains type 2 diabetes SNPs and belongs to the Calpain family of genes, which have been linked to type 2 diabetes when overexpressed by impairing insulin exocytosis in beta cells." (PMID 37311878, 2023). "Accumulating evidence indicates that the poor prognosis of liver cancer is associated with type 2 diabetes and the blockage of insulin signalling pathways in hepatocytes." (PMID 38067256, 2023). "This CpG site can be mapped to the transcription start site of the WNT5B gene, which has been associated with adipogenesis, insulin secretion, and type 2 diabetes." (PMID 38201877, 2023).
type 2 diabetes (continued). "Determining how high BMI at different time points influences the risk of developing type 2 diabetes and affects insulin secretion and insulin sensitivity is critical." (PMID 37280435, 2023). "Diabetes is a metabolic disorder caused by absolute or relative insufficient secretion of insulin, with type 2 diabetes (T2D) being the most common." (PMID 36901633, 2023). "Type 2 diabetes mellitus (T2DM) is a heterogeneous metabolic disorder characterized by reduced insulin sensitivity and relative insulin deficiency." (PMID 36672125, 2023). "Obesity, a major risk factor for type 2 diabetes, requires enhanced insulin production and adaptive insulin hypersecretion." (PMID 37217659, 2023). "Genome-wide association studies have identified dozens of genetic loci that are associated with an increased risk of type 2 diabetes, many of which are involved in insulin secretion and glucose metabolism." (PMID 37445852, 2023). "Recently it has been suggested that higher BCAA and GlycA levels point to a susceptibility to develop type 2 diabetes already decades before the onset of the disease and that in fact insulin resistance causally affects BCAA metabolism." (PMID 36961590, 2023). "It is the tissue resistance and the relative deficiency of insulin which are the root causes of type 2 diabetes." (PMID 37663700, 2023). "Type 2 diabetes mellitus (T2DM) is a metabolic disease characterized by chronic hyperglycemia caused by insulin resistance or insufficient insulin secretion due to various virulence factors." (PMID 37633882, 2023). "Genetically predicted higher TG was associated with higher type 2 diabetes risk [odds ratio (OR) 1.44 per standard deviation (SD), 95% confidence interval (CI) 1.26 to 1.65], HbA1c and fasting insulin specifically in women." (PMID 36624450, 2023). "Loss of insulin sensitivity underlying type 2 diabetes (T2D) is linked to age and affects also IGF-I sensitivity, as both ILPs are functionally interrelated in the control of glucose handling and probably in other functions." (PMID 38003628, 2023). "GPR21 belongs to class A orphan GPCR and is a novel treatment target for type 2 diabetes, primarily caused by systemic insulin resistance." (PMID 36721851, 2023). "Impaired insulin signaling (“resistance”) in humans underlies development of type 2 diabetes, a pandemic disease causing significant morbidity and mortality." (PMID 36730473, 2023). "These genes affect pancreatic β-cell function and insulin secretion, and their polymorphisms have been shown to be associated with the development of type 2 diabetes." (PMID 37628646, 2023). "Higher intake of different types of dietary fibers and phytochemicals derived from fruit and vegetables was also associated with improved insulin sensitivity and lower risk of developing type 2 diabetes." (PMID 37684573, 2023). "As was mentioned before, TMAO can induce ER stress through PERK and FoxO1 activation, leading to the expression of INSR and insulin cellular resistance and elevating the risk of developing type 2 diabetes." (PMID 36830968, 2023). "Although previous observational studies can identify the relationship between Glucose, Type-2 Diabetes, Insulin and the risk of Melanoma, however, because of research confounding variables, a causal association cannot be established." (PMID 38179409, 2023). "Dysregulation of these functions can lead to systemic alterations in insulin sensitivity, inflammation, and atherosclerosis, which are associated with major health conditions, such as type 2 diabetes (T2D) and cardiovascular disease (CVD)." (PMID 37189751, 2023). "Lignans such as sesamin found in sesame seeds were reportedly capable of regulating gene expression associated with insulin signaling, glycogen synthesis, and glucose metabolism in type 2 diabetic rats." (PMID 37959677, 2023).